CCL2 (C-C motif chemokine ligand 2)
Diseases named in the same sentence as CCL2 in open-access papers (continued):
Sharing a sentence is not in itself a finding about the gene and the disease.
neurodegenerative disease (48 papers, 2009 to 2025). A disorder of the central nervous system characterized by gradual and progressive loss of neural tissue and neurologic function. "Many of these genes, such as MMP9 and CCL2, have been previously implicated in blood–brain barrier disruption, leukocyte migration, and cytokine signaling in neurodegenerative disease models." (PMID 41614741, 2025). "Particularly, in the context of neurodegenerative disease, CCL2 and VSIR have been associated with microglial activation and neuroinflammation." (PMID 41279937, 2025). "CCL2 is a pro-inflammatory chemokine implicated in neurodegenerative disease progression." (PMID 38003682, 2023). "Accordingly, CCL2 deficiency reduces infiltration of macrophages into blood vessels, lung and central nervous system in experimental animal models of inflammatory and neurodegenerative diseases, including HSV-1 encephalitis." (PMID 29600197, 2018). "Cytokine CCL2 is involved in neurodegenerative diseases and is upregulated in patients with intractable epilepsy." (PMID 38361811, 2024). "They found that ACKR2-V41A has decreased binding to CCL2 as well as CCL4, another pro-inflammatory chemokine implicated in neurodegenerative disease progression." (PMID 38003682, 2023). "Although the present study focused on RHI, increases in CCL2 has been found in various neurodegenerative diseases and other injuries." (PMID 33278887, 2020). "CCL2 plays an important role in mediating inflammatory response in various neurodegenerative diseases." (PMID 28870240, 2017). "A substantial body of evidence exists suggesting CCL2 is involved in many neuroinflammation and neurodegenerative diseases." (PMID 28870240, 2017). "Monocyte chemoattractant protein-1 (MCP-1, also known as CCL2) may influence BBB leakage and macrophage polarization, impacting neuronal loss and the progression of neurodegenerative diseases, such as AD." (PMID 40153574, 2025). "CCL2 has been demonstrated to play an important role in various neurodegenerative diseases." (PMID 28870240, 2017). "Therefore, intervention aimed at suppressing CCL2/MCP-1 expression is an emerging therapeutic strategy for the treatment of neurodegenerative diseases." (PMID 22339770, 2012). "From a therapeutic point of view, the manipulation of CCL2 may have beneficial effect in neurodegenerative diseases." (PMID 22319587, 2012). "An understanding of cell type-specific CCL2 production may ultimately enable the targeting of this chemokine for enhancing or inhibiting immune cell recruitment to the brain during specific stages of neuroinflammatory and neurodegenerative diseases." (PMID 38206985, 2024). "Thus, CCL2, a multi-potent pathological factor, could be established as a therapeutic target to prevent or treat neurodegenerative diseases." (PMID 32103758, 2020). "These pathways were, in general, shared across all neurodegenerative diseases, even though the major overlap was found for the synaptic functions (BDNF, CCL2, ACHE, GFAP, NEFH or NEFL) and microglia pathways (TREM2, IL13, IL6R IFNG)." (PMID 41250190, 2025). "The inflammatory mediators elicited by endotoxin and PA assessed in the study included proinflammatory cytokine IL-6, chemokine MCP-1 (CCL-2), and prostaglandin PGE2, which are all important in the CNS and neurodegenerative diseases." (PMID 37571401, 2023). "Studies have shown that cytokines released from neurons, including CCL2, CCL21, HMGB1, CGRP, Substance P, CX3CL1, MMP2, and MMP9, can mediate microglia activation in brain injury, neuropathic pain, or neurodegenerative diseases." (PMID 36131309, 2022). "The comparison across multiple neurodegenerative diseases suggest that convergent mechanisms between AD and CTE such as pathologic protein deposition and normal aging can also increase CCL2 levels through mechanisms distinct from RHI." (PMID 33278887, 2020).
neurodegenerative disease (continued). "We have analyzed chemokines CCL2, CCL5 and IL-8; as well as cytokines TNF-α and IL-1β as they are known to be involved in the pathogenesis of neurodegenerative diseases including PD." (PMID 26275153, 2015). "Increased production ofastrocytic CCL2 and CXCL1 was observed in nerve tissue damaged by brain ischemiaand neurodegenerative diseases." (PMID 23627909, 2013). "The identified hub genes—particularly MMP9, CCL2, and S100A8/A9—may serve as promising candidates for therapeutic intervention or biomarker development across multiple neurodegenerative diseases." (PMID 41614741, 2025). "Chemokine (C-C motif) ligand 2 (CCL2) may be involved in the pathways recruiting microglia in chronic traumatic encephalopathy, a progressive neurodegenerative disease." (PMID 36353631, 2022). "In degenerative diseases, upregulated CC chemokines MCP-1 (CCL2), MIP-1α (CCL3), and RANTES (CCL5) are possibly involved in the migration of endothelial progenitor cells during tissue repair, with MCP-1 and MIP-1α able to mobilize mesenchymal stem cells into ischemic brain lesions." (PMID 29109449, 2017). "CCL2 and CCL5 play a crucial role in the brain, but their alterations have not been well studied in systemic immunity in neurodegenerative diseases." (PMID 25635231, 2014).
kidney (47 papers, 2006 to 2025). "This protective effect is, at least in part, mediated by a reduction in CCL2 levels, monocytic infiltration, and overall kidney inflammation." (PMID 40755453, 2025). "The brown cluster focuses on kidney pathologies, especially on calcium oxalate crystal formation and on the role of monocytes-macrophages and the chemokine ligand 2 (CCL2), also known as monocyte chemoattractant protein 1 (MCP-1), in this pathology." (PMID 37901222, 2023). "Expression levels of acute kidney injury markers Kim1 and Lcn2, and cytokines Ccl2 and Cd68, were lower in the cisplatin-injected Dpep1+/− mice when compared to wild-type littermates." (PMID 34426578, 2021). "A novel finding in our model is that at early stages, we observe increases in tubular acute kidney injury markers (Shh, Ccl2, and Kim1), which likely has a significant role in driving disease pathogenesis." (PMID 27853247, 2016). "Decreased nuclear WTAP in NASH leads to the impairment of the WTAP/HDAC1 axis and increases the transcription of Igfbp1, Cd36 and Ccl2, which further increases lipolysis in WAT, hepatic FFA uptake and liver inflammation, respectively, finally causing NASH pathogenesis." (PMID 35927268, 2022). "In an animal model of liver inflammation, microglia activated by TNFa signals were shown to produce MCP1 and CCL2, and recruited monocytes expressing CCR2 into the brain, resulting in a significant infiltration of activated monocytes into the brain." (PMID 33553004, 2020). "This correction of critical metabolic pathways on gene expression level was accompanied by a significant decrease in histological liver inflammation, and suppression of FFD‐stimulated cytokine and chemokine proteins KC/CXCL1, MCP‐1/CCL2, and MIP‐2/CXCL2 and their pathways." (PMID 35830259, 2022). "Apart from CCL2, the rest of the secreted factors that we describe are shown for the first time to be LPA-induced in proximal TECs, and this may have an impact on several kidney pathologies." (PMID 35806457, 2022). "We compared noncancerous and lung‐adenocarcinoma human samples for hypoxia‐inducible factor 1‐alpha (HIF‐1A), microRNA‐210‐3p (mir‐210‐3p), and CCL2 levels." (PMID 35658112, 2024).
neurological disorders (39 papers, 2012 to 2026). "As CCL2 is an inflammatory chemokine, the CCL2/CCR2 axis has been suggested to be involved in HIV-associated neurologic disorders." (PMID 29085362, 2017). "Consistent with this, the polymorphisms in the CCL2 gene have been linked to increased MCP-1 levels in cerebrospinal fluid and monocyte infiltration of brain tissue in HIV-1 associated neurological disorders." (PMID 28501927, 2017). "Although we did not investigate how this inflammation correlates with the pathology related to a specific neurological disease, the role of CCL2-mediated inflammation in pathological settings needs to be clarified." (PMID 23866683, 2013). "It has earlier been established that chronic activation of PBMCs via CCL2/CCR2 signaling pathway mediates inflammation in many neurological disorders." (PMID 22685564, 2012). "For that reason, it is not surprising that chemokines such as CXCL1 and CCL2, among others, have been implicated in a number of neurological diseases." (PMID 37371384, 2023). "However, there is accumulating evidence that many neurological diseases are attributable to a dysregulation of CCL2 expression." (PMID 31681324, 2019). "The findings summarized here classify HIV/SIV Nef-induced CCL2 expression in the complex pathogenesis of HAND, and once again highlight the special role which the CCL2-CCR2 axis can play in a neurological disease." (PMID 31681324, 2019). "Nevertheless, these findings suggest that CCL2 gene expression in brain may also be subjected to AEI and potentially could explain the increased CCL2 levels seen in CSF in individuals bearing rs1024611G allele and their increased susceptibility to HIV-1 related neurological disorders." (PMID 23166687, 2012). "P. gingivalis LPS induces the expression of interleukin (IL)-6 and C-C motif chemokine ligand 2 (CCL2) in the brain microvascular endothelial cells, which may contribute to dysfunction of the BBB and subsequent neurological disorders." (PMID 35959396, 2022).
retinopathy (24 papers, 2008 to 2025). "The antiinflammatory effect of minocycline at the early stage of pericyte-depletion retinopathy was corroborated by the downregulation of CCL2, iNOS, TSPO, and LGALS3 in minocycline-treated APB5 retinas at P10." (PMID 40591415, 2025). "In experimental oxygen-induced retinopathy, mice were treated with the combination therapy of Ccl3- and Ccl2-neutralising antibodies, rather than a singular therapy." (PMID 26911327, 2016). "In addition, we have demonstrated that IL-6 strongly correlates with chemokines in the diabetic group (r=0.74 for CCL2; r=0.86 for CXCL8), indicating that the increased levels are likely downstream effects of elevated IL-6 seen in eyes with retinopathy." (PMID 22511846, 2012).
adenocarcinoma (21 papers, 2005 to 2025). A common cancer characterized by the presence of malignant glandular cells. "Since CCL2 neutralization suppressed human adenocarcinoma-associated pleural vascular permeability, this approach could also be effective against human MPE." (PMID 23967166, 2013). "CCL2 and CCL4 overexpression was associated with beneficial OS and PFS in squamous NSCLC, but unfavorable OS and PFS in adenocarcinoma NSCLC." (PMID 33230935, 2021). "Adenocarcinomas had higher levels of MCP1/CCL2 and MIP‐1β/CCL4 than squamous NSCLC." (PMID 33230935, 2021). "Injection of adenocarcinoma cells transfected +/–CCL2 complementary DNA +/- LPS i.p." (PMID 31921102, 2019). "CCL2 transcript was found increased in CRC tissues compared with tissues from controls, and its protein levels were upregulated in adenocarcinoma compared with the control." (PMID 36433652, 2022). "Here we show that two available CCL2 and CCL12 antagonists alone or in combination are effective in limiting MPE induced by murine and human adenocarcinomas." (PMID 23967166, 2013). "We conclude that CCL2 and CCL12 blockade are effective against experimental MPE induced by murine and human adenocarcinoma in mice." (PMID 23967166, 2013). "Collectively, these results indicated that CCL2 and CCL12 neutralization are equally effective against MPE induced by two different mouse adenocarcinomas." (PMID 23967166, 2013).
cardiac disease (19 papers, 2007 to 2026). "The chemokine C–C ligand 2 (CCL2) or monocyte chemotactic protein-1 (MCP-1) is primarily associated with heart disease, including ischemic heart and cardiac fibrosis." (PMID 37306727, 2023). "Previous studies suggested that CCL2 was upregulated in cardiac injury and was the key culprit for cardiac disease development and progression by promoting the infiltration of mononuclear cells." (PMID 35646094, 2022). "Both, CCL2 and IL-10, are potential indicators of cardiac tissue inflammation and heart disease in experimental models and human in the last decades." (PMID 28377930, 2017). "Other cytokines (TNF-alpha, IL-4, IL-17, IFN-gamma, CCL2, and IL-10) have shown differences between severe chagasic heart disease and the undetermined stage but not between the different stages of chagasic heart disease progression." (PMID 32455143, 2020).
infectious disease (17 papers, 2010 to 2024). A disorder directly resulting from the presence and activity of a microbial, viral, or parasitic agent in humans. "In the LPS-induced infectious disease model, there was a significant increase in chemokines (CCL2), proinflammatory cytokines (IL1β, IL6, TNFα), and a marked decrease in MCH." (PMID 38654385, 2024). "Single nucleotide polymorphisms (SNPs) found in CCL2 and CCL5 gene (chromosome 17), in CCR2 and CCR5 gene (chromosome 3) have been related to infectious diseases including West Nile virus, dengue, HIV24,25, Hepatitis C26 and tuberculosis." (PMID 29057937, 2017). "Not only in infectious diseases, transition of adenine (A) to guanine (G) at CCL2 (−2518) locus i.e. rs1024611G signify important risks for variety of non communicable diseases." (PMID 29057937, 2017). "Given four teas could inhibit the downstream signaling transduction of MCP-1/CCL2 in the inflammatory model, tea extracts may develop as prophylactic strategies for the spread of infectious diseases." (PMID 36135185, 2022). "Notably, the induction of the cognate chemokine ligands such as CCL2, CCL7, and CCL8 are regulated by IFNs-I in certain infectious diseases." (PMID 22911155, 2012).
immune diseases (15 papers, 2009 to 2025). "Targeting CCL2–CCR2 axis has shown a good outcome in mouse models, but anti-CCL2 mAbs or CCR2 antagonists are mainly used to treat immune diseases in the clinical trials." (PMID 36246629, 2022).
peripheral neuropathy (13 papers, 2011 to 2025). A disorder affecting the peripheral nervous system. "Paclitaxel increases IL-6, TNF-α, and CCL2 production in dorsal root ganglia neurons, and IL-6 neutralizing antibody pretreatment prevents peripheral neuropathy development, suggesting the role of increased inflammation in peripheral neuropathy development." (PMID 40759570, 2025). "For example, paclitaxel increases the expression of pro-inflammatory factors like Tlr4, TNF-α, IL-1β, IL-6, and Ccl2/Mcp1 in rodent models of paclitaxel-induced peripheral neuropathy." (PMID 38673862, 2024). "Elevated Ccr2 and Ccl2 expression have been previously observed in the dorsal root ganglia following the administration of another anticancer agent, paclitaxel, and this was positively correlated with peripheral neuropathy." (PMID 30906773, 2019). "Furthermore, studies have reported sensitisation of DRG primary sensory neurons in PTX-induced peripheral neuropathy through induction of monocyte chemoattractant protein-1(MCP-1/CCL2) and its receptor CCR2, as well as toll-like receptor 4 (TLR-4) signalling in the DRG via MAP kinases and NFkB." (PMID 28125674, 2017).
psychiatric disorder (13 papers, 2009 to 2026). A disorder characterized by behavioral and/or psychological abnormalities, often accompanied by physical symptoms. "Chemokines like CCL2 and CXCL8 are upregulated, guiding immune cell migration to both the skin and brain, contributing to skin inflammation and psychiatric disorders." (PMID 41393358, 2026). "C-C motif chemokine ligand 2 (CCL2) is reported to be involved in the pathogenesis of various neurological and/or psychiatric diseases." (PMID 35354428, 2022).
hematological malignancies (9 papers, 2018 to 2025). "Noteworthy, patients with hematological malignancies have increased serum levels of CCL2, IL‐6 and IL‐8 that have been associated with symptoms and with a poor prognosis." (PMID 40511387, 2025). "Monocyte chemoattractants, such as C-C motif chemokine ligand 2 (CCL2) and its homologous receptor C-C chemokine receptor type 2 (CCR2), are targeted for the treatment of solid tumors and hematological malignancies using monoclonal antibodies and receptor antagonists." (PMID 40302816, 2025).
inflammatory myopathies (9 papers, 2009 to 2025). "The CCL2 I/D polymorphism has been recently reported to be associated with development of inflammatory myopathies." (PMID 19357773, 2009). "CCL2 is a key chemokine implicated in the regulation of migration and infiltration of monocytes/macrophages, and together these findings support the utility experimental model for studying inflammatory myopathy." (PMID 41348866, 2025).
respiratory disease (9 papers, 2011 to 2025). "CXCL9, CCL2, IL6, CXCL10, and IL8 have been linked to various respiratory diseases and retain sensitivity for their level estimates as well." (PMID 40650062, 2025).
vasculopathy (9 papers, 2012 to 2025). "CCL2 is involved in pathogenic processes during all stages of transplantation, including vasculopathy and fibrosis." (PMID 37382267, 2023). "Histological analysis of affected tissues from mice treated with SSc PBMCs (SSc hu-mice) demonstrated substantial inflammation, fibrosis and vasculopathy with human immune cell infiltration and increased expression of IL-17, TGF-β, CCL2, CCL3, and CXCL9." (PMID 36175484, 2022).
CNS tumors (5 papers, 2015 to 2025). "Pro-angiogenic inflammatory chemokine CCL2, which is normally a monocyte chemoattractant implicated in macrophage recruitment, is also one of important factors in the progression and development of CNS tumors." (PMID 32456359, 2020). "It was demonstrated that not only normal human brain tissues, but also CNS tumors may express CCL2 constitutively." (PMID 32456359, 2020).
heart (5 papers, 2008 to 2022). "CC motif chemokine receptor 2 (CCR2), which binds C-C motif chemokine ligand 2 (CCL2, also termed monocyte chemoattractant protein-1, MCP-1), plays a fundamental role in the mobilization and recruitment of monocytes to the ischemic heart." (PMID 36555456, 2022).
blood cancers (3 papers, 2021 to 2025). "Thus, there is evidence for the role of the CCL2/CCR2 axis in blood cancers." (PMID 34804061, 2021).
brain disorder (3 papers, 2023 to 2025). A disease affecting the brain or part of the brain. "This would suggest that a pharmacological reduction of biologically active CCL2 has therapeutic potential in ischemic conditions and presumably also in other brain disorders with a neuroinflammatory component." (PMID 39272984, 2024). "C–C motif chemokine ligand 2 (CCL2), also known as monocyte chemoattractant protein-1 (MCP-1), plays a critical role in BBB disruption and neuroinflammation across various brain disorders." (PMID 40548298, 2025).
gynecological tumors (2 papers, 2022 to 2023). "Although the functions of CCL2 in gynecological tumors have been basically defined, the mechanisms of CCL2 in the gynecological tumor microenvironment are still unclear and need further exploration." (PMID 36403055, 2022). "Understanding the role of CCL2 and its regulators in the microenvironment of gynecological tumors could lead to novel discoveries." (PMID 36403055, 2022). "Consequently, CCL2/CCR2 axis can also be further studied as a new target for gynecological tumor therapy." (PMID 36403055, 2022).
hematologic cancer (2 papers, 2017 to 2022). "Within the hematologic cancer patient cohort there was a striking increase in the levels of the chemokines CCL2, CCL3, CCL4, CXCL8, and the cytokine IL-1β, in the Severe-Death group compared to the Mild group." (PMID 36700209, 2022). "We also observed increased concentrations of CCL2, CCL3, CCL4, VEGFA and IL-1β in Severe-Death hematologic cancer patients." (PMID 36700209, 2022).